PPAT (phosphoribosyl pyrophosphate amidotransferase)
Description:
Catalyzes the formation of phosphoribosylamine from phosphoribosylpyrophosphate (PRPP) and glutamine.
Synonyms: ATase; GPAT; PRAT
Tractability: Small molecule: an approved drug acts on it; it belongs to a druggable protein family. PROTAC: ubiquitination databases record sites on it; its protein half-life has been measured.
Target class: Enzyme; Transferase
Gene: Protein-coding gene on chromosome 4 (56,393,362 to 56,435,616, reverse strand). Ensembl gene ENSG00000128059.
Subcellular location (Human Protein Atlas): Midbody ring
Pathways (Reactome):
Metabolism: Purine ribonucleoside monophosphate biosynthesis
Gene Ontology:
Molecular function: protein binding; amidophosphoribosyltransferase activity
Biological process: purine nucleotide biosynthetic process; 'de novo' AMP biosynthetic process; 'de novo' IMP biosynthetic process; 'de novo' XMP biosynthetic process; GMP biosynthetic process; purine nucleobase biosynthetic process
Cellular component: cytosol
Genetic constraint (gnomAD): Loss-of-function variants: 17 observed, 49.65 expected, observed/expected ratio (o/e) 0.34, 90% interval 0.23 to 0.51. The upper end of that interval is the gene's LOEUF score, 0.51, which puts it in group 2 of 6, group 1 being the genes least tolerant of losing a copy. Missense variants: 317 observed, 602.45 expected, observed/expected ratio (o/e) 0.53, 90% interval 0.48 to 0.58. Synonymous variants: 179 observed, 209.38 expected, observed/expected ratio (o/e) 0.85, 90% interval 0.76 to 0.97.
Homologues: Orthologues: chimpanzee PPAT (99% identical), macaque PPAT (99% identical), rabbit PPAT (95% identical), dog PPAT (94% identical), rat Ppat (93% identical), mouse Ppat (93% identical), guinea pig PPAT (93% identical), pig PPAT (93% identical), tropical clawed frog ppat (80% identical), zebrafish ppat (74% identical), Drosophila melanogaster Prat (61% identical), Drosophila melanogaster Prat2 (61% identical).
Diseases named in the same sentence as PPAT in open-access papers:
PPAT is named in the same sentence as 54 diseases in open-access papers, as found by Europe PMC text mining. Sharing a sentence is not in itself a finding about the gene and the disease. The quoted sentences say what the papers report.
lung carcinoma (9 papers, 2015 to 2024). "Tan I downregulates the expression of PPAT, which in turn enhances the radiosensitivity of radiation-resistant lung cancer cells (H358-IR and H157-IR cells), thereby inhibiting cell proliferation." (PMID 36172186, 2022). "Breast, brain, and lung cancer cells manifested a relatively high PPAT/GLS1 ratio, whereas stomach and colorectal cancer cells showed a low PPAT/GLS1 ratio." (PMID 32184390, 2020). "We investigated the functional significance of the de novo purine biosynthetic pathway genes PPAT and PAICS in lung cancer by loss-of-function analyses of these divergently transcribed and elevated in lung tumors." (PMID 26140362, 2015). "Furthermore we identified genomic amplification and aneuploidy of the divergently transcribed PPAT-PAICS genomic region in a subset of lung cancers." (PMID 26140362, 2015). "CLDN10-AS1 might play a role in the development and progression of lung cancer, by regulating the G1/S transition of mitotic cell cycle through miR-125b-5p/PPAT and by regulating endothelium development, angiogenesis, and cell-cell adherens junction through miR-125b-5p/CDH5, respectively." (PMID 32149133, 2020). "In this study, we demonstrate that de novo purine biosynthetic pathway enzymes PPAT and PAICS show increased expression in lung cancer and can serve as prognostic markers for patient survival." (PMID 26140362, 2015). "Our data demonstrate that PPAT and PAICS of de novo purine biosynthesis show increased expression in lung cancer compared to normal lung." (PMID 26140362, 2015). "These in vitro experiments underscore role of PPAT, PAICS and PKM2 in proliferation and invasion across a cross-section of lung cancers cells." (PMID 26140362, 2015). "PPAT and PAICS are two such genes that are co-transcribed from locus 4q12 and show genomic amplification in small percentage of lung cancer cases." (PMID 26140362, 2015). "In summary, we identified increased expression of PPAT and PAICS in de novo purine biosynthetic pathway that is potentially useful for lung cancer prognosis." (PMID 26140362, 2015). "We further confirmed the increased expression of divergently transcribed PPAT, PAICS as well as PKM2 expression in lung cancer samples compared to normal samples by next-generation RNA sequencing and quantitative RT-PCR analysis." (PMID 26140362, 2015). "We discovered aneuploidy and amplification in the divergently transcribed locus of PPAT and PAICS in a subset of lung adenocarcinoma (∼3% cases) and amplification in H661 lung cancer cell line." (PMID 26140362, 2015). "Elevated levels of enzymes involved in the de novo biosynthetic pathway, such as PPAT and PAICS, have been observed in lung cancer and may serve as potential prognostic markers." (PMID 37393565, 2023). "In addition, we showed the critical role of PPAT and PAICS in lung cancer progression both in vitro and in vivo." (PMID 26140362, 2015). "In addition, Affymetrix microarray analyses showed enhanced expression of PPAT, PAICS and PKM2 in poorly differentiated and stage 3 lung cancers (respectively)." (PMID 26140362, 2015). "In summary, this study reveals the regulatory mechanisms by which purine biosynthetic pathway enzymes PPAT and PAICS, and pyruvate kinase activity is increased and exposes an existing metabolic vulnerability in lung cancer cells that can be explored for pharmacological intervention." (PMID 26140362, 2015). "The authors showed that an increase in phosphoribosyl pyrophosphate amidotransferase (PPAT) and PPAT/GLS ratio is required to trigger nitrogen shift towards nucleotide biosynthesis in lung cancer and could be considered as a universal phenomenon in other cancer types apart from colorectal cancer." (PMID 35158820, 2022). "Interestingly, we discovered that PPAT and PAICS knockdown substantially diminished pyruvate kinase activity that is comparable to the PKM2 knockdown suggesting that PKM2 could be an important contributor of the pyruvate kinase activity in lung cancer cell lines." (PMID 26140362, 2015).
breast carcinoma (6 papers, 2002 to 2023). "It is interesting that estradiol stimulation was observed to enhance amidophosphoribosyltransferase (PPAT) gene expression in breast cancer cells, which are involved in PRPP conversion to 5-phosphoribosyl-1-amine (PRA) for purine de novo synthesis." (PMID 35269866, 2022). "PPAT expression by estrogen receptor α signaling pathway also promoted folate-mediated one-carbon metabolism and subsequent cell survival and growth in breast cancer." (PMID 33520699, 2020). "This study reveals the metabolic pathways involved in estrogen-mediated monocarbon, purine and polyamine synthesis in breast cancer, and the discovery that PPAT and AZIN1 were direct ERa targets for the cell survival and growth of breast cancer." (PMID 31391919, 2019). "Cells with a high PPAT/GLS1 ratio such as BT-549 breast cancer cells, TGW neuroblastoma cells, and U-251 MG glioblastoma cells were sensitive to PPAT depletion or GLS1 overexpression with regard to their anchorage-independent growth." (PMID 32184390, 2020).
lung adenocarcinoma (6 papers, 2015 to 2023). A carcinoma that arises from the lung and is characterized by the presence of malignant glandular epithelial cells. "Expression of PPAT and PAICS was independently associated with patient survival in lung adenocarcinomas; further, a subset of adenocarcinoma patients harbour aneuploidy and amplification in divergently transcribed loci of PPAT and PAICS." (PMID 34205450, 2021). "Notably, PPAT was over-expressed, at least partially, through genomic amplification in lung adenocarcinoma and its expression was associated with cancer aggression." (PMID 33520699, 2020). "Among these genes, phosphoribosyl amidotransferase (PPAT) was demonstrated to serve as prognostic biomarkers for aggressive lung adenocarcinoma." (PMID 36861063, 2023). "Research of PPAT in lung adenocarcinomas showed that, PPAT regulated tumour progression via purine biosynthetic pathway." (PMID 35685372, 2022). "PPAT gene was identified as a prognostic biomarker in aggressive lung adenocarcinoma by RNA-Seq analysis." (PMID 29088818, 2017). "We showed that PPAT and PAICS of de novo purine biosynthesis are up-regulated in lung adenocarcinomas." (PMID 26140362, 2015). "Tissue microarray analysis by immunohistochemistry (IHC) using specific antibodies against PPAT and PAICS showed increased staining in lung adenocarcinomas." (PMID 26140362, 2015). "Transcript analyses from next-generation RNA sequencing and gene expression profiling studies suggested that PPAT and PAICS can serve as prognostic biomarkers for aggressive lung adenocarcinoma." (PMID 26140362, 2015). "In order to identify the possible genomic events for PPAT and PAICS dysregulation, we performed fluorescence in situ hybridization (FISH) with lung adenocarcinoma samples." (PMID 26140362, 2015). "Varambally‘s laboratory reported that PPAT and another enzyme PAICS in the purine biosynthesis pathway may drive lung adenocarcinoma cells to switch to aerobic glycolysis (the Warburg Effect)." (PMID 33520699, 2020). "Thus amplification could be one of the potential mechanisms of increased expression of PPAT and PAICS in a subset of lung adenocarcinomas." (PMID 26140362, 2015). "We discovered increased expression of phosphoribosyl amidotransferase (PPAT) and phosphoribosylaminoimidazole carboxylase, phosphoribosylaminoimidazole succinocarboxamide synthetase (PAICS) enzymes of de novo purine biosynthetic pathway in lung adenocarcinomas." (PMID 26140362, 2015).
small cell lung carcinoma (5 papers, 2020 to 2025). Small cell lung cancer (SCLC) is a highly aggressive malignant neoplasm, accounting for 10-15% of lung cancer cases, characterized byrapid growth, and early metastasis. "This pathway has been reported to contribute to the progression of small cell lung cancer, where phosphoribosyl pyrophosphate amidotransferase (PPAT) has been identified as a key enzyme." (PMID 40552664, 2025). "In small cell lung cancer, phosphoribosyl pyrophosphate amidotransferase (PPAT), a key enzyme of DNPS, can synergize with glutaminase (GLS) to determine the metabolic fate of glutamine within the cell, thereby sustaining DNA replication and tumor cell proliferation." (PMID 40097378, 2025). "Large-scale proteomic and metabolomic analyses revealed perturbations in nitrogen metabolism across the series, implicating a high phosphoribosyl pyrophosphate amidotransferase (PPAT)/GLS1 ratio in small cell lung cancer and other malignancies through increased nucleotide synthesis." (PMID 39332495, 2024). "PPAT expression is particularly strong in small cell lung carcinoma; thus, the tricarboxylic acid cycle is inhibited in the mitochondria, which may explain the low Mito-score." (PMID 38565653, 2024). "Moreover, Nakayama and coworkers recently demonstrated that PPAT played essential roles in nitrogen metabolic reprograming particularly in neuroendocrine cancer including small cell lung cancer." (PMID 33520699, 2020).
melanoma (4 papers, 1992 to 2024). A malignant, usually aggressive tumor composed of atypical, neoplastic melanocytes. "The same has been observed in P493-6 cells for PPAT and PFAS, in human melanoma SK-MEL-19 cells for PPAT, as well as in activated T lymphocytes for both PPAT and CAD." (PMID 34503295, 2021). "In addition, it has been demonstrated that c-Myc plays a critical role in the maintenance of expression of PRPS2, PPAT, TrifGART, PAICS and IMPDH2 in melanoma cells and of PPAT, IMPDH1, IMPDH2 but not PAICS in a human lymphoma model cell line." (PMID 38444943, 2024).
colorectal cancer (3 papers, 2020 to 2025). A primary or metastatic malignant neoplasm that affects the colon or rectum. "Clinical data analysis revealed a significantly higher transcriptional level of PPAT in colorectal cancer tissues, and its expression intensity was found to be negatively correlated with the survival rate of patients." (PMID 41394399, 2025). "Instead of PPAT, hypoxanthine phosphoribosyltransferase 1 (HPRT1) was significantly associated with poor prognosis in colorectal cancer, suggesting that the salvage pathway of nucleotide biosynthesis is dominant over the de novo pathway in this cancer type." (PMID 32184390, 2020). "The relation of the PPAT/GLS1 ratio to prognosis in colorectal cancer appeared opposite to that in the other types of cancer." (PMID 32184390, 2020).
leukemia (3 papers, 2014 to 2020). A malignant (clonal) hematologic disorder, involving hematopoietic stem cells and characterized by the presence of primitive or atypical myeloid or lymphoid cells in the bone marrow and the blood. "Although AICART inhibition and the accumulation of AICAR and its metabolite AICA have been proposed to mediate anti-inflammatory effects, in vitro studies with leukemia cells and primary human T lymphocytes indicate that PPAT is the primary site of inhibition of purine biosynthesis by methotrexate." (PMID 25255447, 2014). "Therefore, we performed additional in vitro experiments based on the two best 5-protein models (which shared TYMP, RRM1, UPP1, and UCK1 and contained either PPAT or UCK2) using two CRC and two leukemia cell lines that are predicted to be sensitive or resistant to 5FU." (PMID 32686665, 2020).
neuroendocrine carcinoma (3 papers, 2020 to 2023). A malignant neuroendocrine neoplasm composed of cells containing secretory granules that stain positive for NSE and chromogranin. "The observation that PPAT expression was significantly associated with poor prognosis for neuroendocrine cancer prompted us to investigate whether such expression is also related to the outcome of SCLC, which is thought to be a high-grade neuroendocrine cancer." (PMID 32184390, 2020). "PPAT is also strongly correlated with malignancy, particularly in neuroendocrine cancer including small cell lung cancer (SCLC), and its depletion suppresses the growth of SCLC lines." (PMID 35676822, 2023). "Of note, PPAT and GLS1 expression was significantly associated with poor (HR = 5.21) or tended to be associated with good (HR = 0.38) prognosis, respectively, in neuroendocrine cancer." (PMID 32184390, 2020).
glioblastoma (2 papers, 2020 to 2021). The most malignant astrocytic tumor (WHO grade IV). "Increased levels of ADSL, adenylosuccinate synthase (ADSS), IMPDH1, and PPAT are associated with poor prognosis in glioblastoma patients." (PMID 34205450, 2021). "Additionally, overexpression of PPAT, IMPDH1, and ADSS correlate with worse survival among glioblastoma patients." (PMID 34205450, 2021).
Hypertension (2 papers, 2016 to 2020). The presence of chronic increased pressure in the systemic arterial system. "PPAT and FXR1 are pivotal molecules in the control of blood pressure circadian rhythm by the kidney in hypertension." (PMID 33463674, 2020).
liver cancer (2 papers, 2020 to 2025). An epithelial or non-epithelial malignant neoplasm that arises from the liver. "This Kaplan–Meier survival analysis based on a large public liver cancer dataset indicated that high expression levels of PPAT, along with other five DNPS genes, were correlated with poor prognosis." (PMID 40097378, 2025).
atherosclerosis (1 paper, 2024). A disease characterized by the build-up of fatty material and calcium deposition in the arterial wall resulting in partial or complete occlusion of the arterial lumen. "GART, TYMS, PPAT, and CTPS1 had the strongest association with inflammation, followed by atherosclerosis and cerebral infarction." (PMID 38995420, 2024).
brain tumors (1 paper, 2020). "Overexpression of PPAT and ADSL is associated with poor survival of patients with brain tumors." (PMID 32218208, 2020).
colorectal tumors (1 paper, 2016). "On the basis of our gene expression data we may generalize, that colorectal tumors irrespective of the stage and localization share common downregulation of DPYD and upregulation of PPAT, UMPS, RRM2, and SLC29A1 transcripts." (PMID 27733154, 2016).
Friedreich ataxia (1 paper, 2020). An inherited condition that affects the nervous system and causes movement problems. "PPAT maturation and subsequent function are affected in the neurodegenerative disorder Friedreich Ataxia." (PMID 33023155, 2020).
renal cell carcinoma (1 paper, 2023). "SHMT2 improves the m6A abundance of PPAT mRNA by offering methyl donor SAM, allowing IGF2BP2 to enhance the stability and expression of PPAT, regulating cell cycle to promote proliferation in renal cell carcinoma." (PMID 37280679, 2023).
thyroid cancer (1 paper, 2021). "And they identified that PPAT plays a crucial role in regulating proliferation, migration, and invasion of thyroid cancer." (PMID 33614667, 2021).